SIRT1 (sirtuin 1)
Diseases named in the same sentence as SIRT1 in open-access papers (continued):
Sharing a sentence is not in itself a finding about the gene and the disease.
heart failure (continued). "Some studies have described that under stress or heart failure conditions, SIRT1 translocates into the nucleus and activates an antioxidant response." (PMID 41018278, 2025). "It is well-known that SIRT1 probably provides a new therapeutic regimen for preventing heart failure and plays an important role in the occurrence and development of myocardial fibrosis." (PMID 38561456, 2024). "Ginsenoside Rg1 inhibits cardiac remodeling in heart failure through SIRT1/PINK1/Parkin-mediated mitochondrial autophagy." (PMID 39141645, 2024). "For example, cardiomyocyte‐specific expression of Larp7 protects against heart failure by activating Sirt1‐Pgc1a‐mitochondrial pathway." (PMID 38818612, 2024). "In conclusion, our in vivo findings showed that the SIRT1-AMPK-PGC-1α signaling pathway was inhibited during heart failure, which is consistent with previous studies." (PMID 37089931, 2023). "This review presents the progress of research involving SIRT1 pathway involvement in the pathophysiological mechanisms of myocardial remodeling and heart failure." (PMID 36843938, 2023). "For instance, RSV has been shown to improve the survival rate of rats with heart failure by activating SIRT1 and SIRT3-mediated autophagy and improving hemodynamics and energetics." (PMID 37754811, 2023). "Sirtuin-1 (SIRT1) is a highly conserved histone deacetylase that has a protective role in the treatment of heart failure by regulating the deacetylation of some functional proteins." (PMID 36757027, 2023). "To further support the role of SIRT1-regulated α-MHC lactylation, we found that SIRT1 expression was decreased in cardiac tissues of patients and mice with heart failure, as well as in Ang II-induced H9c2 cells." (PMID 37443257, 2023). "Sirt1 mRNA and protein expression were significantly decreased, and the acetylation levels were increased in heart failure." (PMID 36757027, 2023). "This article reviews the role and molecular mechanisms of Sirt1 protein in myocardial remodeling and outlines the specific mechanisms by which Sirt1 improves different types of myocardial remodeling and heart failure." (PMID 36843938, 2023). "Preclinical data indicate that SIRT1 is a promising target - increasing evidence suggests that SIRT1 activation ameliorates or prevents myocardial remodeling, delaying the progression of heart failure." (PMID 36843938, 2023). "This study revealed that by activating Sirt1, resveratrol effectively hindered ferroptosis in heart failure, decelerated the progression of cardiac fibrosis, and enhanced the cardiac function of mice." (PMID 37487007, 2023). "Like SIRT1, the declined activity of SIRT3 associated with aging is associated with endothelial dysfunction, hypertension, and heart failure." (PMID 36093141, 2022). "Leukocytes and biopsies of the left atrial myocardium derived from human patients have suggested that SIRT1 protein is downregulated in heart failure, corresponding with increased oxidative stress and apoptosis." (PMID 36062878, 2022). "SIRT1 has also been reported to play a cardioprotective role during heart failure by modulating the expression of antioxidant enzymes and reducing ROS." (PMID 36355510, 2022).
heart failure (continued). "Conversely, downregulation of Sirt1 is observed in cardiomyocytes from patients with advanced heart failure; indeed, the whole AMPK/Sirt1/NAMPT axis appears to be downregulated in the aging/failing heart." (PMID 36139463, 2022). "The oxidative stress-miR-199a-SIRT1 axis is a specific pathway for the occurrence of ischemia-driven heart failure and LV dysfunction." (PMID 33802566, 2021). "Using these animal models along with in vitro experiments, we found that mangiferin protected against MI‐induced cardiomyocyte apoptosis and heart failure by activating the Sirt1/FoxO3a pathway." (PMID 33523605, 2021). "Echinacoside improves the heart function by the SIRT1/FOXO3a/MnSOD signaling pathway in heart failure rats." (PMID 34513812, 2021). "The reduced expression of SIRT1 is consistent with the increased levels of acetylation found in heart failure." (PMID 33802566, 2021). "In mice, mangiferin treatment increased Sirt1 expression after MI, significantly reduced the infarct area, and prevented MI‐induced apoptosis and heart failure." (PMID 33523605, 2021). "Administration of epicatechin-rich cocoa in an experiment of T2D human patients suffering from heart failure enhanced the expressions of SIRT1 and PGC-1α and consequently enhanced the biogenesis of mitochondria among skeletal muscle." (PMID 34336094, 2021). "Epicatechin-rich cocoa administration throughout a study in T2D human patients suffering from heart failure expressed an increase in the SIRT1 and PGC-1α expression that promoted mitochondrial biogenesis in skeletal muscle." (PMID 34336094, 2021). "As a sensitive energy regulator, SIRT1 translocates to the nucleus during heart failure, participates in mitochondrial biogenesis by deacetylating PGC-1α, and thereby regulates energy metabolism." (PMID 31866862, 2019). "In a minipig model of heart failure, transplanted stem cell cultures from wild type showed more proliferation compared to transplants from SIRT1 knockout stem cell sheets." (PMID 28197299, 2017). "Similar to this, the Lewis rat model of heart failure also showed lesser cardiac function in a SIRT1 knockout stem cell transplants." (PMID 28197299, 2017). "Sirt1 expression increases (12-fold) in hearts of dogs with experimental heart failure induced by rapid pacing." (PMID 29234485, 2017). "These experiments explain that SIRT1 mediates regenerative capability of stem cells in heart failure." (PMID 28197299, 2017). "It has been shown that sirtuin 1 (SIRT1) is downregulated in patients with heart failure, and that there is an increase in sirtuin 1 reducing oxidative stress-mediated cardiac reperfusion injury." (PMID 26391855, 2015). "Sirt1 was down-regulated (54.92% ± 7.80% in advanced heart failure samples compared with healthy control cardiomyocytes)." (PMID 24913149, 2014). "The metabolism of nutrition in the myocardium will change substantially during advanced heart failure, however, further experiments are necessary to elucidate the role of Sirt1 on the metabolic remodeling of the failing heart." (PMID 24913149, 2014). "The expression of both AMPK and Nampt was also decreased (0.60 ± 0.06-fold and 0.52 ± 0.08-fold vs. donor, respectively) in advanced heart failure as Sirt1’s expression." (PMID 24913149, 2014). "The AMPK-Nampt-Sirt1 axis also showed inhibition in advanced heart failure in addition to severely impaired AMPK activation." (PMID 24913149, 2014). "Sirt1’s expression as observed using immunohistochemistry showed reduced nuclear expression (decreased to 52.74 ± 12.72% compared to donor) with advanced heart failure." (PMID 24913149, 2014). "Since both AMPK and Nampt are the upstream molecules of the functional signaling pathway of the AMPK-Nampt-Sirt1 axis, we examined their expression in advanced heart failure." (PMID 24913149, 2014).
heart failure (continued). "SIRT1 can regulate endothelial nitric oxide to protect against cardiovascular disease, exert a cardioprotective role in heart failure, and protect against neurodegenerative pathological changes." (PMID 22152608, 2011). "SIRT1 plays an important role in the process of improving heart failure." (PMID 40710369, 2025). "Therefore, investigating the molecular mechanisms of heart failure via the AMPK/SIRT1/PGC-1α energy metabolism pathway is a critically important research direction." (PMID 40994651, 2025). "Activation of SIRT1 plays a crucial role in mitigating EndMT by modulating the neurogenic locus notch homolog protein 1 (Notch1) and TGF-β/Smad2/3 pathways, thereby reducing fibrotic responses associated with heart failure." (PMID 41011644, 2025). "Moreover, in animal models of heart failure with preserved ejection fraction (HFpEF), SIRT1 inhibits cardiac fibrosis via the Smad3 pathway." (PMID 41011644, 2025). "SIRT1 was found to improve cardiac function, reduce ventricular mass, and decrease apoptosis in cardiomyocytes by inhibiting the acetylation of NF-κB p65, leading to a decrease in the expression of NF-κB p65, which ameliorates heart failure." (PMID 40710369, 2025). "Hence, the ability of resveratrol to inhibit ferroptosis and exhibit therapeutic benefits in the treatment of advanced heart failure in mice is dependent on Sirt1." (PMID 37487007, 2023). "A heart failure model was established by aortic coarctation in Sirt1 knockout mice." (PMID 37487007, 2023). "The aim of this study was to determine whether H2S could increase SIRT1 activity to protected against heart failure and to unravel its potential role." (PMID 36757027, 2023). "However, the SIRT1 level was decreased more in CSE KO mice compared with wild-type mice in ISO-induced heart failure." (PMID 36757027, 2023). "Several studies have shown that long non-coding RNAs have the tendency to interact with SIRT1 in several diseases/conditions, including cardiac failure, non-alcoholic fatty liver disease, and ischemic stroke, most of which are considered as aging-related diseases." (PMID 38136198, 2023). "In summary, we demonstrated that H2S directly S-sulfhydrated SIRT1 at zinc figure domains to activate SIRT1 to protective against heart failure treatment with H2S may serve as a therapeutic approach to attenuate heart failure development in humans." (PMID 36757027, 2023). "However, Sirt1 knock‐out ameliorated the inhibitory effect of resveratrol on cardiomyocyte ferroptosis and its improvement of heart failure in mice." (PMID 37487007, 2023). "Therefore, α-MHC K1897 lactylation and α-MHC–Titin interaction cannot be significantly rescued during heart failure by inhibiting SIRT1." (PMID 37443257, 2023). "Taking into account the close relationship between myocardial remodeling and heart failure and the involvement of SIRT1 in the development of the former, the role of SIRT1 in the prevention of heart failure via inhibition of myocardial remodeling has received considerable attention." (PMID 36843938, 2023). "Sirtuin-1 (SIRT1) is a highly conserved nicotinamide adenine dinucleotide (NAD+)-dependent class III histone deacetylase that may play a crucial role in heart failure." (PMID 36757027, 2023). "However, the ability of resveratrol to prevent ferroptosis and treat heart failure was lost after silencing Sirt1." (PMID 37487007, 2023). "SIRT1 has beneficial effects on the development of heart failure." (PMID 36581622, 2022). "Importantly, the increased oxidative stress correlated with decreased SIRT1 expression during the development of heart failure." (PMID 35351862, 2022). "Interestingly, SIRT1 expression which decreases with aging correlated with the onset and development of heart failure and even ST-segment elevation myocardial infarction (STEMI)." (PMID 36093141, 2022).
heart failure (continued). "Previous reports showed that PPARα acts as a cofactor of Sirt1 and may repress mitochondrial gene transcription, leading to heart failure." (PMID 33073318, 2021). "Our results indicate that mangiferin prevents cardiomyocyte apoptosis and the subsequent heart failure by activating the Sirt1/FoxO3a pathway in MI, and suggest that mangiferin may have an interesting potential in following studies towards clinical evaluation." (PMID 33523605, 2021). "Our study indicates that the miR199a-5p/Sirt1/P300/Yy1/sST2 axis might be a potent therapeutic approach for treating heart failure." (PMID 33594087, 2021). "However, suppression of the estrogen-related receptor transcriptional pathway by PPARα/SIRT1 as a physiological fasting response is involved in the progression of heart failure by inducing mitochondrial dysfunction." (PMID 33806509, 2021). "Our previous study demonstrated that the NAD-dependent deacetylase Sirt1 is upregulated in pressure overload-induced heart failure in mice, concurrent with the increased interaction with PPARα (PGC-1α's binding partner), resulting in downregulation of genes involved in OXPHOS and FAO." (PMID 32083094, 2020). "In the early stage of heart failure, the expression of SIRT1/SIRT3 in the myocardium may be stimulated by chemical and mechanical factors to compensate the functional lost." (PMID 31866862, 2019). "However, similar as PGC-1α, the function of SIRT1 overexpression in heart failure is closely related to its levels." (PMID 31866862, 2019). "In heart failure, resveratrol, a potent SIRT1 activator, could increase AMPK expression and alleviate cardiac dysfunction through SIRT1 activation." (PMID 30123131, 2018). "Collectively, activation of PGC-1α by SIRT1 and enhanced mitogenesis may restore energy metabolism in the failing myocardium and ameliorate heart failure." (PMID 22622703, 2012). "Notably, exercise improves energy metabolism in heart failure models by upregulating the SIRT1-NAMPT axis, indicating that targeting this pathway may represent a key strategy for exercise-mediated cardiovascular protection." (PMID 41009469, 2025). "Besides, miRNAs that modulate expression of SIRT1 can affect pathogenesis of heart failure." (PMID 37441551, 2023). "Therefore, H2S protected against heart failure via activating SIRT1." (PMID 36757027, 2023). "Moreover, ET could be able to promote sirtuin-1 (SIRT1) and better antioxidant activity in heart failure (HF) patients." (PMID 32266263, 2020). "Whether Sirt1 activates or inhibits PGC-1α in the context of heart failure remains unknown." (PMID 32083094, 2020). "Besides, some studies examining the effects of resveratrol indicate that Sirt1 may have a beneficial role in failing hearts and that endogenous Sirt1 up-regulation is a protective mechanism in the early stage of heart failure." (PMID 31503544, 2019). "Therefore, development of drugs targeting at up-regulation of SIRT1/SIRT3 may be an effective direction for the treatment of heart failure." (PMID 31866862, 2019). "Downregulation of Sirt1 may have important meaning in the advanced heart failure, though cause and effect relationship is not yet established in our observation." (PMID 24913149, 2014).
heart failure (continued). "Its AMPK/SIRT1/PGC-1α signaling pathway activation restored mitochondrial homeostasis, which slows the development of heart failure by raising ATP levels and lowering ROS levels." (PMID 41567643, 2025). "This study is to investigate the regulatory mechanism of over‐expression or knock‐down SIRT1 gene, alleviating hypoxia‐induced HK2 cell fibrosis in heart failure." (PMID 40197776, 2025). "Our results identify four factors, p300, SIRT1, LDHA, and the intracellular lactate concentration, as regulators of α-MHC K1897 lactylation during heart failure." (PMID 37443257, 2023). "Conversely, in subjects with heart failure, a significant reduction of Sirt1 expression is observed in cardiomyocytes: indeed, the whole AMPK/Sirt1/Nampt axis appears to be downregulated in the aging/failing heart." (PMID 36674711, 2023). "The treatment with NaHS significantly upregulated the levels of SIRT1 and PGC-1α in ISO-induced heart failure mice." (PMID 36757027, 2023). "Compared to SIRT1, SIRT3, and SIRT6, studies on SIRT2,541 SIRT4, SIRT5,542 and SIRT7 in heart failure are limited." (PMID 36581622, 2022). "Therefore, the present study is aimed at investigating whether a supervised 4-week ET-CR program was able to induce changes in Sirt1 activity and βOHB levels and to evaluate the possible relationship between such parameters, in Heart Failure with preserved Ejection Fraction (HFpEF) patients." (PMID 31885811, 2019). "Due to lower expression of Sirt1 and MnSOD in heart failure, translocation of transcriptional factor FoxO1, which could modulate the expression of MnSOD, was examined, Immunostaining revealed decreased FoxO1 in the nucleus in advanced heart failure cardiomyocytes." (PMID 24913149, 2014). "Regardless of the stressor, downregulation of Sirt1 in the heart was associated with loss of cardioprotection in the literatures, such as our result that low expression of Sirt1 in advanced heart failure may lead to additional irreversible heart injury via downstream effectors." (PMID 24913149, 2014). "Biological functions of SIRT1/SIRT3 are described in this review, mainly from the viewpoint of translation into therapy for heart failure." (PMID 22622703, 2012). "In this study, we report that Wenxin Keli (also known as Wenxin granule), a clinically available Chinese patent medicine used for preventing and treating heart failure–related arrhythmias, modulates energy metabolism and improves Cx43 function by activating AMPK/SIRT1/PGC-1α signaling pathway." (PMID 40994651, 2025). "As far as the possible underlying molecular mechanisms are concerned, recent studies have investigated the possible role in heart failure (HF) of sirtuins, a family of nicotinamide adenine dinucleotide (NAD+)-dependent deacetylases, among which sirtuin 1 (Sirt1) is the best characterized member." (PMID 38921661, 2024). "We consider that the main reason that α-MHC K1897 lactylation cannot be rescued by inhibiting SIRT1 during heart failure is the lack of lactate in cardiomyocytes." (PMID 37443257, 2023). "Concurrently, SIRT1 inhibition may rescue the reduction in α-MHC K1897 lactylation and α-MHC binding to Titin during heart failure." (PMID 37443257, 2023).